CDK13 (cyclin dependent kinase 13)
Description:
Cyclin-dependent kinase which displays CTD kinase activity and is required for RNA splicing. Has CTD kinase activity by hyperphosphorylating the C-terminal heptapeptide repeat domain (CTD) of the largest RNA polymerase II subunit RPB1, thereby acting as a key regulator of transcription elongation. Required for RNA splicing, probably by phosphorylating SRSF1/SF2. Required during hematopoiesis. In case of infection by HIV-1 virus, interacts with HIV-1 Tat protein acetylated at 'Lys-50' and 'Lys-51', thereby increasing HIV-1 mRNA splicing and promoting the production of the doubly spliced HIV-1 protein Nef.
Synonyms: hCDK13; CDC2L; CDC2L5; CHED; KIAA1791; CHDFIDD
Tractability: Small molecule: a drug acting on it is in phase 2 or 3 trials; a structure with a bound ligand is known; a high-quality ligand is known; it belongs to a druggable protein family. Antibody: its Gene Ontology location is reachable by antibodies, with high confidence. PROTAC: it is named in the literature on targeted protein degradation; UniProt records ubiquitination sites on it; ubiquitination databases record sites on it; its protein half-life has been measured; a small molecule that binds it is known.
Target class: Enzyme
Chemical probes: BSJ-01-175 (high quality), MFH290 (high quality), SR-4835 (high quality), THZ531 (high quality)
Gene: Protein-coding gene on chromosome 7 (39,950,121 to 40,099,580, forward strand). Ensembl gene ENSG00000065883.
Subcellular location: Nucleus speckle
Subcellular location (Human Protein Atlas): Nuclear speckles; Cytosol; Golgi apparatus
Pathways (Reactome):
Immune System: Neutrophil degranulation
Gene Ontology:
Molecular function: cyclin binding; protein binding; RNA binding; RNA polymerase II CTD heptapeptide repeat kinase activity; protein kinase activity; ATP binding; cyclin-dependent protein serine/threonine kinase activity; protein kinase binding; protein serine kinase activity
Biological process: hemopoiesis; positive regulation of transcription by RNA polymerase II; positive regulation of transcription elongation by RNA polymerase II; regulation of signal transduction; alternative mRNA splicing, via spliceosome; regulation of cell cycle
Cellular component: cyclin K-CDK13 complex; extracellular region; nuclear speck; cyclin/CDK positive transcription elongation factor complex; ficolin-1-rich granule lumen; nuclear cyclin-dependent protein kinase holoenzyme complex; nucleoplasm; cyclin-dependent protein kinase holoenzyme complex
Genetic constraint (gnomAD): Loss-of-function variants: 27 observed, 85.73 expected, observed/expected ratio (o/e) 0.31, 90% interval 0.23 to 0.43. The synonymous counts are far from expectation, so gnomAD's model fits this gene poorly and the ratio says little. Missense variants: 1,570 observed, 1,454.3 expected, observed/expected ratio (o/e) 1.08, 90% interval 1.03 to 1.12. Synonymous variants: 769 observed, 582.83 expected, observed/expected ratio (o/e) 1.32, 90% interval 1.24 to 1.4.
Gene-disease validity (ClinGen):
ClinGen rates the evidence that CDK13 causes each of these diseases.
syndromic intellectual disability (autosomal dominant): Definitive. A intellectual disability that is part of a larger syndrome.
Homologues: Orthologues: chimpanzee CDK13 (99% identical), macaque CDK13 (99% identical), dog CDK13 (97% identical), mouse Cdk13 (95% identical), pig CDK13 (95% identical), rat Cdk13 (95% identical), tropical clawed frog cdk13 (51% identical), zebrafish cdk13 (46% identical), Drosophila melanogaster Cdk12 (26% identical). Paralogues in human: CDK12 (43% identical), CDK11B (13% identical), CDK11A (13% identical), PRP4K (12% identical), CDK17 (12% identical), CDK16 (11% identical), CDK18 (11% identical), CDK9 (11% identical), CDKL5 (11% identical), CDK14 (10% identical), CDK19 (10% identical), CDK8 (10% identical), and 14 more.
Diseases named in the same sentence as CDK13 in open-access papers:
CDK13 is named in the same sentence as 71 diseases in open-access papers, as found by Europe PMC text mining. Sharing a sentence is not in itself a finding about the gene and the disease. The quoted sentences say what the papers report.
Intellectual disability (11 papers, 2018 to 2025). "Germline mutations of the CDK13 gene cause a neurodevelopmental disorder with developmental delay and intellectual disability, whereas somatic mutations are linked to carcinogenesis." (PMID 41440036, 2025). "In our ASD cohort, we identified a de novo heterozygous missense variant in CDK13 in a male patient with cognitive impairment, moderate intellectual disability, and ASD." (PMID 40558542, 2025). "Pathogenic variants in CDK13 cause CDK13‐related disorder in humans, characterised by intellectual disability and developmental delay, recognisable facial features, feeding difficulties and structural brain defects, with 35% of individuals having CHD." (PMID 39556044, 2025). "Cardinal features of CDK13-related disorders are characterized by intellectual disability, developmental delay, dysmorphic facial features, structural heart defect and structural brain abnormality." (PMID 35651941, 2022). "Since the identification of CDK13, CAMK2B and RALA as syndromic, intellectual disability genes, we assume that the involvement of CDK13, CAMK2B and RALA genes in the deletion of our patient explains the presence and the severity of the intellectual disability." (PMID 34828280, 2021). "Mutations in the kinase domain of CDK13 were previously found to be related to a syndromic form of intellectual disability with or without congenital heart disease." (PMID 31941532, 2020). "These patients demonstrate that heterozygous, likely dominant negative mutations affecting the protein kinase domain of the CDK13 gene result in a recognisable, syndromic form of intellectual disability, with or without congenital heart disease." (PMID 29021403, 2018). "In summary, this study adds further evidence to support mutations in the kinase domain of CDK13 as a cause of a clinically recognisable form of syndromic intellectual disability, with or without congenital heart disease, most likely by a novel dominant negative mechanism." (PMID 29021403, 2018). "These children had no intellectual disability or facial dysmorphism, which is present in CDK13‐related disorder." (PMID 39556044, 2025). "For example, phosphosites on CDK13, TCF20 and NONO, genes that are known to be strongly associated with intellectual disability, exhibit varying temporal profiles (Sup." (PMID 39282277, 2024).
developmental delay (9 papers, 2018 to 2025). "In particular, overall developmental delay, incomplete secondary palate formation with variability in severity among Cdk13-deficient animals or complete midline deficiency, kidney failure accompanied by congenital heart defects were detected." (PMID 31440507, 2019). "Spectrum of clinical phenotypes of patients with CDK13 mutations varies from mild to severe with the ubiquitous intellectual disability and developmental delay (ID/DD)." (PMID 31440507, 2019). "We report here 10 different missense mutations and 1 canonical splice-site mutation, all within the PK domain of CDK13 in sixteen individuals with a syndromic developmental delay phenotype." (PMID 29021403, 2018). "Although no clinical diagnostic criteria have been published, the clinical findings of developmental delay and facial dysmorphic features are suggestive, and the diagnosis of CDK13-related disorder primarily depends on molecular genetic testing." (PMID 31883531, 2019).
prostate carcinoma (9 papers, 2021 to 2025). A carcinoma that arises from epithelial cells of the prostate gland. "Our prior work in numerous prostate cancer models revealed the two kinases to have a synthetic lethal relationship—such that genetic ablation or pharmacologic inhibition of CDK13 preferentially impairs tumor cell survival in the setting of CDK12 inactivation." (PMID 40504161, 2025). "In the mechanism of prostate cancer, CDK13 interacts with NSUN5, promoting its phosphorylation at the Ser327 site." (PMID 41462962, 2025). "Our recent study found that miR-212-5p/miR-449a inhibits the expression of E2F5 and mediates circCDK13/CDK13 feedback regulation to promote the occurrence and development of prostate cancer." (PMID 34692488, 2021). "CDK13 expression is upregulated and fatty acid synthesis is increased in prostate cancer." (PMID 41462962, 2025). "Furthermore, CDK12 deficiency has been found to exhibit synthetic lethality when its paralog CDK13 is pharmacologically targeted, suggesting that this could be a promising novel treatment approach for this type of prostate cancer." (PMID 41465280, 2025). "CDK12BAL cells showed a vulnerability to targeting of CDK13 by sgRNA or CDK12/13 inhibitors and in vivo treatment of prostate cancer xenograft lines showed that tumors with CDK12BAL responded to the CDK12/13 inhibitor SR4835, while CDK12-intact lines did not." (PMID 39071291, 2025). "The critical dependency of prostate cancer cells on CDK12 and CDK13 for proliferation was further recently corroborated by CRISPR-mediated gene editing." (PMID 39353441, 2024). "Increased sensitivity of AR-positive (compared to AR-negative) prostate cancer cell lines to THZ1, an inhibitor of CDK7/CDK12/CDK13, has been previously reported." (PMID 37076563, 2023).
hepatocellular carcinoma (6 papers, 2012 to 2025). A malignant tumor that arises from hepatocytes. "The pro-oncogenic role of CDK13 was also suggested in hepatocellular carcinomas, where the CDK13 locus is amplified and correlates with age of clinical onset in a subset of patients." (PMID 39533070, 2025). "Previous study has demonstrated high levels of RNA editing in the CDK13 gene in hepatocellular carcinoma." (PMID 38835016, 2024). "Supporting our results in thyroid cancer, CDK13 editing correlated with poor prognosis in hepatocellular carcinoma." (PMID 34496885, 2021). "After CDK13 amplification was described in hepatocellular cancer, CDK13 was consequently proposed to be an oncogene." (PMID 29090014, 2017). "More precisely, a SNP-chip based study showed aberrant higher copy numbers of CDK13 gene correlated with increased expression in primary hepatocellular carcinomas (HCCs) and colorectal cancer." (PMID 26886422, 2016). "CDK13 was described as amplified in hepatocellular carcinoma and exhibits oncogenic activity." (PMID 34496885, 2021).
breast carcinoma (5 papers, 2021 to 2024). "At the mRNA level, overexpression of CDK7 or CDK8 was associated with inferior prognosis, whereas higher CDK13 expression was associated with favorable prognosis in breast cancer patients." (PMID 33686962, 2021). "Survival analysis showed that although higher mRNA expression of CDK13 in breast cancer was significantly associated with favorable RFS and OS in the Kaplan-Meier Plotter, genetic alteration in transcription-associated CDKs was instead associated with shorter OS in cBioPortal." (PMID 33686962, 2021). "Prior research has shown that downregulating CDK13 suppresses colony formation in a breast cancer cell line." (PMID 38835016, 2024). "Related to this, CDK12 and CDK13 inhibition in breast cancer induces immunogenic cell death and enhances PD-1 immunotherapy, while on the other hand, defective transcriptional elongation is described to confer immunotherapy resistance for some cancers." (PMID 38132164, 2023). "In our study, the expression levels of CDK13 in breast cancer tissues were significantly higher than in normal breast tissues." (PMID 33686962, 2021). "Our results indicate that CDK7, CDK8, and CDK13 could be prognostic biomarkers for breast cancer patients." (PMID 33686962, 2021). "Survival analysis of breast cancer patients revealed that increased CDK8 expression was associated with inferior overall survival (OS), higher expression of CDK7 or CDK8 was associated with inferior relapse-free survival (RFS), but higher expression of CDK13 was associated with favorable RFS and OS." (PMID 33686962, 2021). "The optimal compound 7f effectivelydegraded CDK12 and CDK13 with DC50 values of 2.2 and 2.1nM, respectively, in MDA-MB-231 breast cancer cells." (PMID 35938508, 2022). "Thus, CDK12/CDK13 inhibitors may be a promising treatment option for breast cancer." (PMID 33686962, 2021). "CDK13 and CDK19 were not expressed or lowly expressed in normal breast tissues, whereas medium expression of these two proteins was observed in breast cancer tissues." (PMID 33686962, 2021).
congenital heart disease (5 papers, 2017 to 2025). A heart disease that is present at birth. "De novo missense variants in CDK13 have been described as the cause of syndromic congenital heart defects in seven individuals ascertained from a large congenital cardiovascular malformations cohort." (PMID 28807008, 2017). "Recent evidence has emerged linking mutations in CDK13 to syndromic congenital heart disease." (PMID 29021403, 2018). "After the recent discovery of CDK13 as the cause of congenital heart defects, facial dysmorphism and intellectual developmental disorder (CHDFIDD), we aimed to further delineate the phenotypic spectrum, dysmorphology and medical co-morbidities of this newly described syndrome." (PMID 28807008, 2017). "Congenital heart defects, facial dysmorphism and intellectual developmental disorder (CHDFIDD) is a newly described syndrome caused by de novo variants in CDK13." (PMID 28807008, 2017). "Since CDK13-related CHDFIDD was initially discovered in a large exome sequencing congenital heart disease cohort, all initial patients were selected for study based upon their expressed cardiac disease." (PMID 28807008, 2017). "CDK13-related disorder is a rare autosomal dominant disease characterized by dysmorphic facial features and intellectual developmental disorder with or without congenital heart disease." (PMID 38910624, 2024).
melanoma (5 papers, 2023 to 2026). A malignant, usually aggressive tumor composed of atypical, neoplastic melanocytes. "Similar to CDK12 loss, CDK13 mutations lead to the accumulation of short RNAs and prematurely terminated intronic RNAs, which can accelerate melanoma oncogenesis." (PMID 41491919, 2026). "CDK13 loss of function in melanoma has been linked to impaired RNA surveillance." (PMID 39800748, 2025). "However, recent evidence showed that loss of function mutations in CDK13 are found in melanoma patients, highlighting an unexpected and hitherto unproven role for CDK13 as tumour suppressor." (PMID 39533070, 2025). "Of note, both melanoma and non-melanoma skin cancers show exceptionally high frequencies of CDK12 and CDK13 mutations across all cancers." (PMID 41491919, 2026). "In contrast to its oncogenic properties observed in various cancers, CDK13 has been identified as a tumor suppressor in melanoma." (PMID 39800748, 2025). "CDK13’s involvement in cancer proliferation has been explored in prostate, ovarian, colorectal, melanoma, and breast cancers, exhibiting both oncogenic and tumor-suppressive properties depending on the context." (PMID 39800748, 2025). "To assess the role of CDK12 in melanoma cells, we treated five BRAF-mutated melanoma cell lines (Colo829, A375, WM164, WM983A, WM983B) with increasing concentrations of SR-4835, a recently described ATP-competitive inhibitor of CDK12 and CDK13." (PMID 38104154, 2023).
ovarian carcinoma (5 papers, 2021 to 2025). A malignant neoplasm originating from the surface ovarian epithelium. "Taken together, these data demonstrate that CDK12 loss increases dependence on CDK13, rendering ovarian cancer cells sensitive to CDK13/12 degraders." (PMID 40504161, 2025). "Furthermore, ovarian cancer patients harbouring deletions of either CDK12 or CDK13 also carry mutations in at least one other DDR gene, supporting the idea that loss of CDK12/13 is associated with higher tumour mutation burden." (PMID 39533070, 2025). "Analysis of data from The Cancer Genome Atlas (TCGA) indicated that the frequency of alterations in the CDK12 (9%) and CDK13 (2.5%) genes was similar (CDK13) or higher (CDK12) with respect to other DDR genes among ovarian cancer patients (n = 398)." (PMID 37202753, 2023). "Analysis of the same cohort of patients form the PanCancer project showed that CDK12 and CDK13 deep deletions are mutually exclusive with MYC amplification in ovarian cancer." (PMID 37202753, 2023). "A similar distribution was observed also for CDK13, albeit this gene was more frequently amplified than deleted in ovarian cancer patients." (PMID 37202753, 2023). "Other studies showed that the simultaneous inhibition of CDK12 and CDK13 suppresses tumorigenic features in leukemia, ovarian cancer and triple-negative breast cancer." (PMID 34496885, 2021). "We then tested whether pharmacologically targeting CDK13 preferentially killed Cdk12 KO ovarian cancer cells." (PMID 40504161, 2025). "We then employed human OVCAR8 ovarian cancer cells to determine whether CRISPR-based CDK12 ablation also conferred sensitivity to CDK13/12 degrader therapy." (PMID 40504161, 2025). "These analyses support the important role played by CDK12 and CDK13 in ovarian cancer." (PMID 37202753, 2023). "For instance, ovarian cancers that simultaneously express high levels of MYC, CDK12 and CDK13 define a cohort of patients with a pronounced reduction of the overall survival." (PMID 39533070, 2025). "In patient-derived xenografts models from patients with heavily pre-treated ovarian cancer, THZ1 (a chemical that inhibits CDK7, CDK12, and CDK13) repressed MYC expression and suppressed tumor growth." (PMID 33686962, 2021). "Nevertheless, more than 80% of ovarian cancer patients do not present alterations in the CDK12 and CDK13 genes." (PMID 37202753, 2023).
glioblastoma (4 papers, 2021 to 2026). The most malignant astrocytic tumor (WHO grade IV). "Elevated CDK13 editing events have been detected in several tumor types, including glioblastoma and kidney renal clear cell carcinoma." (PMID 38835016, 2024). "Fetal brain, liver, and muscle tissues derived from glioblastoma cDNA libraries also showed high levels of CDK13 expression." (PMID 33879837, 2021). "Here we find that glioblastoma stem cells (GSCs) are selectively sensitive to CDK12/CDK13 inhibition, whereas CDK7 and CDK9 inhibition cause non-specific cytotoxicity." (PMID 41882177, 2026).